IL1A (interleukin 1 alpha)
Diseases named in the same sentence as IL1A in open-access papers (continued):
Sharing a sentence is not in itself a finding about the gene and the disease.
cancer (continued). "Activation of immune cells in response to RT ± human recombinant IL-1α was evaluated in human peripheral blood mononuclear cell (PBMC):cancer cell co-cultures." (PMID 40169985, 2025). "To investigate if exogenous IL-1α would enhance immune cell activation in the presence of RT-exposed cancer cells in vitro, we co-cultured human PBMCs with RT (0–8 Gy)-exposed Cal-27 cells and treated the co-cultures with human recombinant IL-1α (rIL-1α)." (PMID 40169985, 2025). "And the finding demonstrated a strong correlation between elevated levels of immune checkpoints and the SREBF1 in ACC, notably KIR2DL3, IL2RA, CD80, IFNG, BTN3A2, and IL1A, also IFNA1 wass significantly associated with SREBF1 in the majority of cancers." (PMID 40668814, 2025). "Another significant cytokine is IL1α/β, synthesized by cancer and immune cells, which are heavily reliant on NF-κB, and stimulate the MAPK and NF-κB pathways, contributing to tumorigenesis." (PMID 40869207, 2025). "The expression of IL-1α was also prominent in elongated, cord-like clusters of cancer cells invading the surrounding tissue." (PMID 40940885, 2025). "After 24 h of siRNA transfection, the cancer cells exhibited decreased IL-1α mRNA expression and secretion." (PMID 40940885, 2025). "In a further investigation, simulated microgravity stimulated 3D development of PC-3 cancer cells and differential production of the cytokines IL-1α, and IL-1β, indicating their role in PCa cell growth and progression." (PMID 38745115, 2024). "The important role of pro-inflammatory cytokines, including IL-1α, in invasiveness of malignant cells in cancer patients and in different experimental tumors in mice has previously been shown." (PMID 38612760, 2024). "ARG1 expression was the most strongly associated with IL1A, NRG1, CCL1, and CRP in cancer str of the CRC tumors among the numerous associated genes (13 401 genes)." (PMID 38557819, 2024). "IL-1α is a dual function cytokine that affects inflammatory and immune responses and plays a pivotal role in cancer." (PMID 38612760, 2024). "Although IL-1α is mainly retained intracellularly, a naturally occurring human IL-1α neutralizing antibody MABp1 (XBiotech Inc., Austin, TX, USA) and an antibody targeting IL-1α (Bermekimab) have shown promising results with several types of cancers." (PMID 38612760, 2024). "IL-1α is an upstream cytokine that is constitutively expressed in a variety of cells and plays a pivotal role in inflammation and cancer." (PMID 38612760, 2024). "Although IL-1RA was discovered almost concurrently with IL-1α and IL-1β, its value in cancer remains relatively uncertain compared to the other two." (PMID 38339264, 2024). "Compared with the IL-1R ligand IL-1β, less is known on the role of IL-1α-dependent proinflammation in cancer despite it has become an apical regulator of inflammatory response in a much wider cellular scenario due to its unique properties (71, –, 73)." (PMID 38117084, 2024). "The immunohistochemical analysis revealed significantly higher expression of CD44, MYC, IL17A, CXCL1, FCGR3A, SPP1, and IL1A in cancer tissues, while CXCL12 and CCL5 showed significantly higher expression in adjacent normal tissues." (PMID 39767563, 2024). "IL-1α expression has been reported to be significantly increased in many types of human malignant neoplasms and involved in cancer progression and metastasis." (PMID 36982207, 2023). "It is reported that the cardiovascular effects of IL‐1α were similar to that of septic shock and further plans for clinical trials for cancer therapy were discontinued." (PMID 37206237, 2023). "Such is also the case of IL1A, which appears to have a dual role in cancer, and in ccRCC especially, its blocking has been associated with better outcomes." (PMID 38067341, 2023). "Necroptotic cancer cells release interleukin-1a (IL-1a), which activated dendritic cells (DCs) to produce IL-12 (a cytokine essential for antitumor response)." (PMID 37061535, 2023).
cancer (continued). "IL-1α is a crucial cytokine involved in inflammatory processes and promotes the pathogenesis of cancer." (PMID 37580647, 2023). "Yet, IL‐1α drives inflammation, which is one of the hallmarks of cancer, with chronic inflammation both initiating cancer via genotoxic stress, and driving tumorigenesis via cell proliferation, angiogenesis and tissue invasion." (PMID 36175368, 2023). "PaTu8988T amoeboid cells were shown to secrete high levels of interleukins [such as interleukin-1α (IL-1α), IL-5, IL-6, IL-7, IL-8, and IL-9], as well as several chemokines involved in cancer progression." (PMID 37851808, 2023). "Accumulating evidence suggests that IL-1α is involved in cancer pathogenesis and highly expressed by the epithelium of the entire gastrointestinal tract." (PMID 36771338, 2023). "(iii) to explore the role of IL-1α/NF-κB pathway in the regulation of inflammatory secretion and malignant behavior in cancer cells exposed to senescent Spalax secretome." (PMID 36982207, 2023). "In a separate report in 10–15 cancer patients, IL-1α was infused intravenously over 15 min daily for 5 days at doses producing calculated serum concentrations 760–7,600 pg./mL." (PMID 37928695, 2023). "Here we show that CPH:SA IL‐1α‐MPs are potential safe alternatives to rIL‐1α delivery for cancer therapy." (PMID 37206237, 2023). "Recombinant IL‐1 ligands (marketed as Dainippon/Immunex [IL‐1α] and Syntex [IL‐1β]) were administered to cancer patients with the most common symptoms being flu‐like symptoms including fever, chills, rigors and nausea." (PMID 37206237, 2023). "Due to its ubiquitous intracellular expression, potent activity, and bioavailability, IL-1α has emerged as a major drug target in inflammatory diseases and cancer." (PMID 36771338, 2023). "The cytokines interleukin‐1 alpha (IL‐1α) and interleukin‐1 beta (IL‐1β) have also been investigated as anti‐cancer agents in preclinical and clinical studies." (PMID 37206237, 2023). "Bermekimab (MABp1) is a human antibody targeting IL-1α and was used in patients with refractory cancer." (PMID 37701434, 2023). "Intravenous IL-1α was infused over 15 min in 15 cancer patients daily for 7 days with each dose producing calculated serum levels between 255 and 25,450 pg./mL." (PMID 37928695, 2023). "Among the three cytokines, decreasing the expression of IL1α seems to produce the highest reductive effects on cancer metastasis." (PMID 37551997, 2023). "Dysregulation of IL-1α under the influence of Spalax CM, especially the decrease in the level of membrane-bound IL1-α, plays an important role in suppressing inflammatory secretion in cancer cells, which in turn leads to inhibition of cancer cell migration." (PMID 36982207, 2023). "Cancer cell–derived IL-1α induces the recruitment of regulatory T (Treg) cells to foster the formation of an immunosuppressive micromilieu by increasing CCL22 expression." (PMID 35493517, 2022). "To further explore ingredients in the cancer culture medium and their mechanisms for the observed effects on cardiomyocytes, we examined the interleukin-1α (IL-1α), IL-1β, transforming growth factor-β (TGF-β) levels in medium by ELISA." (PMID 35265687, 2022). "IL-1α plays a role in crosstalk between immunocytes and tumors, and it has been targeted in treating several cancers." (PMID 36426368, 2022). "Cancer cells themselves secrete cytokines related to inflammation, such as IL-1α, IL-6, and IL-8, which can activate macrophages." (PMID 35855902, 2022). "CREB3L1 expression in ATC cells facilitated IL-1α-mediated CAFs differentiation, thereby remodeling the cancer niche." (PMID 36192735, 2022). "Two major, closely related IL-1 family members, IL-1α and IL-1β, promote tumorigenic phenotypes and contribute to treatment resistance in cancer." (PMID 35626710, 2022).
cancer (continued). "On the other hand, anakinra (a selective antagonist of the IL-1 receptor, which inhibits both IL-1α and IL-1β) has shown a significant effect in reducing clinical symptoms in different cardiovascular diseases and cancer." (PMID 36611853, 2022). "IL-1 family members, IL-1α and IL-1β, are known to promote cancer cell proliferation, invasiveness, and metastasis." (PMID 33390169, 2021). "Functional disparities between IL-1α and IL-1β blockade in preclinical cancer models have been observed." (PMID 33530653, 2021). "It is of great importance to understand the mechanisms and functions of these different IL-1α isoforms in different inflammatory diseases as well as cancers." (PMID 33430381, 2021). "IL-1α, IL-1β, and IL-18 have been investigated in many types of cancer with both pro- and anti-tumorigenic functions mediated by different cells." (PMID 33840390, 2021). "Recently, it was described an important relationship between IL-1α and inflammation and cancer stem cell (CSCs) in HER2 + breast cancer." (PMID 33840390, 2021). "In this review, we summarize the current understanding of IL-1α processing, signaling, function and its role in cancer progression." (PMID 33430381, 2021). "IL-1α-activated PSC can assist cancer cell migration, which is known to be inhibited by TGF-β via blocking IL-1α-mediated secretion of hepatocyte growth factor and reducing IL-1 receptor expression." (PMID 34988078, 2021). "Here, we review the recent development in the processing and signaling of IL-1α and summarize the functions of IL-1α in cancer development." (PMID 33430381, 2021). "For example, monoclonal antibodies targeting IL-1α or IL-1β have shown promise as potential cancer therapies, and the IL-1 receptor antagonist Anakinra has shown efficacy in pre-clinical models of PDA." (PMID 32329713, 2020). "Concurrently, IL-1α/β interacts with IL-1R on cancer cells to activate an autocrine positive feedback loop." (PMID 32198421, 2020). "Human specific ELISAs on whole lung homogenates from mice bearing MDA-LM2-derived lung metastases further confirmed expression of cancer cell-derived IL-1α/β in metastatic lungs." (PMID 32198421, 2020). "Clinical studies conducted the late 1980s and early 1990s have shown that recombinant IL-1α (marketed as Dainippon and Immunex) can be safely given to human cancer patients." (PMID 30890189, 2019). "IL-1α and IL-1β are amongst the most prominent and potent inflammatory cytokines, together with TGFβ, TNFα, and IL-6, in the TME, and are implicated in cancer-related inflammation." (PMID 31557902, 2019). "In our previous studies of the TMEs of several different cancer types, we found that elevated levels of transcripts for the cytokines IL-1a, IL-10, IL-27 and IL-32 g, in addition to IFN-g, were associated with PD-L1 protein expression." (PMID 31730010, 2019). "IL-1α signaling is involved in inflammatory diseases and cancer, driving cancer progression in different ways." (PMID 31557902, 2019). "MABp1 (XBiotech Inc.)is a naturally occurring human IL-1α neutralizing antibody which has shown promising outcomes in several cancer types." (PMID 31231372, 2019). "An alternative (and not mutually exclusive) explanation for this observation is the heterogeneity of HeLa cancer cells in responding to IL-1α." (PMID 31426445, 2019). "Impressively, the SCNE dramatically depressed key circulating pro-cancer inflammatory cytokines (IFNγ, TNFα, IL-6, IL-1α, and IL-1β) in all of the xenograft and 4NQO-1 mouse models tested." (PMID 31572681, 2019). "Whilst there is no shortage of data supporting a role for IL-1β in tumorigenesis, there are relatively fewer studies directly examining IL-1α in cancer development and progression." (PMID 31231372, 2019).
cancer (continued). "Mechanistically, amoeboid cancer cells perpetuate their behavior via ROCK-Myosin II-driven IL-1α secretion and NF-κB activation." (PMID 30712866, 2019). "Of those modulated genes, SPP1, IL1RN, IL1A, TNFSF13B, OSM, and CSF3 had the most clinical relevance, as their high expression was associated with poor cancer patient overall survival." (PMID 31022845, 2019). "Immunofluorescence analysis of lungs of NSG mice injected with MDA-MB-231 cells showed that cancer cells surrounded by macrophages express IL1α and IL1β as early as 5 days post injection." (PMID 29777109, 2018). "Human Cytokine Array analysis showed that cancer patients have a significant increase in saliva expression of pro-inflammatory markers IL-1a, IL-1b, IL-6, IL-8, and TNFα compared to controls." (PMID 30018735, 2018). "HGF levels produced by PSCs and the effects of PSC media on the cancer cells were increased by IL-1α and inhibited by TGFβ." (PMID 29069737, 2017). "Cancer cells resistant to chemotherapy and oncoprotein-targeted drugs display increased IL-1α, IL-6, IL-8, TNF-α, HGF, EGF, VEGF, GM-CSF and SDF-1α expression." (PMID 28928376, 2017). "Further, IL1A inhibition, by mean of a true humanized antibody (MABp1), showed promising results in refractory cancers." (PMID 27708224, 2016). "We must know the distribution of allelic frequencies of these polymorphisms [IL-1A (rs3783553), IL4 (rs79071878), NFKB1 (rs28362491) and PAR1 (rs11267092)] for association studies on cancer, data for which is limited on Brazilian populations." (PMID 26879815, 2016). "Silencing of endogenous SMAD7 reduced PSC expression of IL-1R1 and attenuated the effects exerted by IL-1α on the ability of PSCs to stimulate cancer cell migration." (PMID 27473228, 2016). "On the other hand, conditioned medium from PSCs stimulated with TGFβ in combination with IL-1α significantly inhibited the migration of cancer cells compared to conditioned medium from IL-1α stimulated PSCs." (PMID 27473228, 2016). "Silencing of stellate cell expression of SMAD7 was found to suppress the levels of IL-1R1 and reduce the stimulatory effects of IL-1α, thus inhibiting the capacity of pancreatic stellate cells to induce cancer cell migration." (PMID 27473228, 2016). "Due to its role in inflammation and cancer development, IL-1α has been used as a biomarker in various in vivo and in vitro models to evaluate the progression of the inflammatory process during cancer development." (PMID 27706097, 2016). "We found that TGFβ reduced the expression of IL-1R1 on PSCs which subsequently diminished their ability to stimulate cancer cell migration upon IL-1α stimulation." (PMID 27473228, 2016). "Pancreatic stellate cells cultured in the presence of IL-1α or in co-cultures with BxPC-3 cells enhanced the migration of cancer cells." (PMID 27473228, 2016). "Recently, it was shown that IL-1α neutralization using a monoclonal antibody would be beneficial in cancer patients in prolonging their survival." (PMID 28083070, 2016). "In the present study, we have demonstrated an inhibitory role of TGFβ in the regulation of IL-1α signaling between cancer cells and pancreatic stellate cells, with subsequent inhibition of the ability of PSCs to enhance cancer cell migration." (PMID 27473228, 2016). "Depletion of SMAD7 upregulated the effects of TGFβ and reduced the expression of IL-1R1, leading to inhibition of IL-1α induced stellate cell enhancement of carcinoma cell migration." (PMID 27473228, 2016). "This strongly suggests that carcinoma cell migration is induced by IL-1α activation of PSCs, which can be inhibited by SMAD7 depletion." (PMID 27473228, 2016). "Our present findings are consistent with the notion of a suppressing role for TGFβ/SMAD signaling in the regulation of the inflammatory PSC profile induced by IL-1α, with subsequent reduced migration of the carcinoma cells." (PMID 27473228, 2016).
cancer (continued). "The MB-downregulated genes include cancer-associated cytokines/chemokines (e.g. CXCL1, CXCL2, CXCL3, CXCL14, IL1A, IL1B, IL6, IL8) and matrix metalloproteinases (MMP1,MMP9)." (PMID 25642713, 2015). "Western blot analysis showed markedly higher IL-1α expression by the highly metastatic cancer cells, while IL-1RI expression in the two cell lines was similar." (PMID 24924428, 2014). "Expression of IL-1α transcript was significantly elevated in all cancer tissue samples investigated compared with normal cervical tissue sample." (PMID 25237386, 2014). "Proof of this mechanism comes from a human trial in which patients with advanced cancer are treated with anti-IL-1α monoclonal human antibody." (PMID 24312098, 2013). "The results showed that mRNA expression and IL-1α production were induced in fibroblasts when treated with cancer cell–conditioned media." (PMID 23593346, 2013). "This study highlights the importance of IL-1α for invasiveness and angiogenic properties in vitro, and confirms that only those cancer cell lines that show highly metastatic properties express IL-1α mRNA." (PMID 23847622, 2013). "Taken together, the blockage of signaling pathways leading to IL-1α expression and/or neutralization of IL-1α in the PDAC microenvironment should be taken into consideration as possible treatment or complement to existing treatment of this cancer." (PMID 23951028, 2013). "Using a HUVEC in vitro model, cancer cells were shown to secret interleukin (IL)-1α to stimulate IL-8 secretion by endothelial cells." (PMID 22911748, 2012). "The possible role of the inflammatory cytokines in the development and spread of cancer cells led us to examine the involvement of leptin in the production of IL-1a, IL-1b, IL-6 and TGF-β1 by human HCC cells." (PMID 20723213, 2010). "We demonstrated that IL-1α stimulation and cancer cell adhesion to collagen type IV enhanced the focal adhesion kinase (FAK) protein association with β1 integrin and FAK phosphorylation." (PMID 16504015, 2006). "We previously reported that the expression of only two subunits, the α6 and β1 integrin subunits, by the high-metastatic cancer cell lines was enhanced by IL-1α, and the adhesive and invasive capability was also enhanced by IL-α." (PMID 16504015, 2006). "In addition to clinical trials, more preclinical studies are warranted to better understand the functions of IL-1α and IL-1β in regulating different stages of cancer development." (PMID 40562870, 2025). "IL-1α is a potent pro-inflammatory cytokine secreted by immune and cancer cells." (PMID 41289612, 2025). "The effect of IL-1α knockdown on the cancer cell phenotype was subsequently evaluated." (PMID 40940885, 2025). "More importantly, EGR146–49, LCN250 and SOCS351 could be upregulated by IL-1α, IL-1β and IL-6 in immune or cancer cells by activating the NF-κB or STAT3 signaling pathway." (PMID 40523992, 2025). "We observed that IL-1α was mainly expressed in cells of myeloid morphology or in cancer cells." (PMID 39820336, 2025). "We found that compared to CTNNB1 WT carcinomas, samples harboring CTNNB1 mutations showed significantly decreased levels of IL1A (p-value = 0.045), IL1B (p-value = 0.12), and caspase 1 (p-value = 0.037), while demonstrating similar IL1R1 and IL1R2 expression levels." (PMID 41227323, 2025). "This occurs not only by actively promoting cancer cell survival through integrin signalling (β1 integrin), mitogen secretion (IL-1α and TGFβ), and oxygen regulation but also by suppressing RT-induced IFN signalling through focal adhesion kinase (FAK) signalling." (PMID 38833685, 2024). "Altogether, our study establishes that the relationship between aging and the host response to cancer is immunologically-driven and that targeting IL-1α-driven emergency myelopoiesis may be a potential immuno-therapeutic strategy." (PMID 39236155, 2024).